CDK4 (cyclin dependent kinase 4)
Diseases named in the same sentence as CDK4 in open-access papers (continued):
Sharing a sentence is not in itself a finding about the gene and the disease.
breast cancer (continued). "Besides their potential utility to select high-risk or highly sensitive patients who might benefit most from CDK4/6 inhibitors in early breast cancer, gene expression signatures have recently been intended for measuring treatment activity as a new endpoint." (PMID 34638325, 2021). "Our novel mutations in NCOR1, MUC4, and MUC16 genes should be validated in further mechanistic studies and translational studies so that those mutations might serve as predictive biomarkers or therapeutic targets for patients with CDK4/6 inhibitor-resistant breast cancer." (PMID 33504001, 2021). "Besides MAPK pathway inhibitors, CDK4/6 inhibitors induce similar responses in breast cancer cells." (PMID 34001994, 2021). "Advances in the understanding of the molecular biology of ER+ breast cancer led to a revolution in this field with the development of a variety of therapeutic agents that are now being used in routine clinical care in patients with metastatic disease such as CDK4/6, PI3K, and mTOR inhibitors." (PMID 32309212, 2020). "Finally, given that CDKN2A mutations have been linked to a worse prognosis and a high likelihood of malignant progression, CDK4/6 inhibitors, which are currently used in breast cancer and have been studied in glioblastoma, can also be of interest in the treatment of patients with IDH-mutant gliomas." (PMID 32444979, 2020). "In addition, a recent study showed that LncRNA TROJAN could mediate resistance to CDK4/6 inhibitors by increasing CDK2 activation in ER+ breast cancer." (PMID 33364954, 2020). "CDK4/6 inhibitors are the breakthrough for the treatment of estrogen receptor‐positive breast cancer (BC) at present." (PMID 33377643, 2020). "Although our data show that targeting PI3K is likely to benefit patients with PIK3CA-mutant ER+/HER2− breast cancer that has progressed on CDK4/6-targeted therapy, targeting mTORC1 may provide another therapeutic option for patients with PIK3CA wild-type breast cancer." (PMID 32795346, 2020). "Recently, treatment with the cyclin-dependent kinase 4/6 (CDK4/6) inhibitor palbociclib in combination with endocrine therapy (ET) was incorporated in the National Comprehensive Cancer Network treatment guidelines for patients with HR+/HER2− advanced breast cancer (ABC)." (PMID 32683565, 2020). "Targeting CDK4/6 signaling in combination with endocrine therapies significantly improves progression-free survival (PFS) overall survival in patients with advanced estrogen receptor-positive /HER2-negative (ER+/HER2−) breast cancer and is now the standard of care for this disease." (PMID 32795346, 2020). "Therefore, targeting FGFR1/2 in luminal breast cancer may be a viable option combined with the inhibition of CDK4/6 to overcome CDK4/6 inhibitor resistance." (PMID 33364954, 2020). "Thus, greater use of ET plus a CDK4 & 6 inhibitor as initial therapy for advanced disease in women with HR+/HER2− advanced breast cancer may have the potential to maintain/improve patient HRQoL." (PMID 32894087, 2020). "MALAT1 via miR-124/CDK4/E2F1 axis could enhance breast cancer progression." (PMID 33330110, 2020). "Palbociclib is a cyclin-dependent kinase 4/6 (CDK4/6) inhibitor, approved in combination with endocrine therapy for the treatment of women and men with hormone receptor–positive, human epidermal growth factor receptor 2–negative advanced breast cancer (HR+/HER2− ABC)." (PMID 32683565, 2020). "Here, we show that the expression of cyclin-dependent kinase 4/6 (CDK4/6) complex members significantly correlates with mutations (as proxies of DNA damages), and that the combination of CDK4/6 and PARP inhibitors shows synergy in both RB-proficient and RB-deficient breast cancer cells." (PMID 32249776, 2020). "Furthermore, we demonstrated that the combined inhibition of CDK2 and CDK4/6 could be a promising approach for treating palbociclib-resistant breast cancer." (PMID 33260316, 2020).
breast cancer (continued). "Despite the fact that the new guidelines for the therapy of advanced breast cancer includes a CDK4/6 inhibitor combined with endocrine treatment as the first- or second-line drug in most countries, most patients eventually develop acquired drug resistance to CDK4/6 inhibitors." (PMID 33364954, 2020). "However, despite the clinical advances associated with the addition of CDK4/6 inhibitors to endocrine therapies, acquired resistance to approved treatments for ER+/HER2− breast cancer remains a significant unmet clinical need, particularly in the metastatic setting." (PMID 32795346, 2020). "However, CDK4/6 inhibitors are only approved for the treatment of breast cancer up to now." (PMID 32929370, 2020). "Furthermore, enforced expression of miR-126-3p in drug treatment-naive non-small cell lung cancer cells, renal cancer cells or breast cancer cells has been shown to increase sensitivity to vincristine and adriamycin, cisplatin, and CDK4/6 or PIK3CA inhibitors, respectively." (PMID 31227006, 2019). "Our findings suggest that the mechanism of CDK4/6 inhibitor resistance exists in multiple forms and that the levels of CDK4 and CDK6 are potential biomarkers of CDK4/6 inhibitors, which may be especially useful for the selection of patients to estimate the sensitivity in breast cancer." (PMID 31448056, 2019). "Our data support the further investigation of OAds in combination with other CDK4/6 inhibitors in vivo to determine the potential of this strategy to prolong the response time and overcome resistance to palbociclib, which will ultimately impact the survival of ER+ breast cancer patients." (PMID 31100952, 2019). "Thus, our findings indicate that CDK4/6 inhibitors, approved for a breast cancer subtype addicted to CDK4/6 activation, could be repurposed to treat SCCOHT." (PMID 30718512, 2019). "In addition, both SCCOHT and breast cancer cell lines express lower levels of CDK4." (PMID 30718512, 2019). "The recent arrival of CDK4/6 inhibitor agents, with an approximate doubling of progression-free survival (PFS) associated with their use in hormone receptor-positive, HER2-negative advanced breast cancer (BC), has radically changed the approach to managing this disease." (PMID 31396487, 2019). "CDK4 is also found to be highly expressed in aggressive tumors and its expression correlate with poor overall and relapse free survival outcomes as well as poor prognostic features of breast cancer patients, suggesting a central role for this protein in cancer development and progression." (PMID 29502166, 2018). "Importantly, it has been found that the CDK4/6 inhibitor palbociclib is able to induce senescence in a breast cancer cell line, highlighting CDK inhibition as an interesting avenue of research in senescence induction and its role against oncogenic transformation." (PMID 30340359, 2018). "In addition, when a panel of 47 human breast cancer and immortalized breast cell lines grown in vitro were treated with a CDK4/6 inhibitor (palbociclib), sensitive cell lines (estrogen receptor positive) showed increased expression of the genes RB1 and CCND1 and reduced expression of CDKN2A (p16)." (PMID 30443290, 2018). "Consequently, CDK4/6 inhibition seems a reasonable target for breast cancer treatment." (PMID 27429659, 2016). "Thus, we investigated the expression of MALAT1, CDK4 and miR-124 in breast cancer tissues." (PMID 26918449, 2016). "Therefore CDKs have attracted much attention in recent years as potential cancer therapeutic targets and selective CDK4/6 inhibitors which potently inhibit the G1 to S phase transition have established their role in the clinic for patients with advanced ER+ breast cancer." (PMID 27486754, 2016). "Recent preclinical data on the efficacy of an ER degrading agent with a CDK4/6 inhibitor in ESR1-mutant breast cancer provides further rationale for this population, because improvements in TTP or OS could be caused by suppression of ESR1-mutant AI-resistant clones." (PMID 26371134, 2015).
breast cancer (continued). "We noticed that compared to control, in DMBA-treated animals levels of Cdk4 and Ccnd1 were increased respectively an average ~3.0- and 1.0-fold in adjacent mammary tissues; and an additional ~6.0- and 12.0-fold increase was seen, respectively, for Cdk4 and Ccnd1, in mammary tumors." (PMID 26715507, 2015). "Enhanced expression of cdk4 may play a role in breast cancer." (PMID 24848372, 2014). "However, E2F in OHT cells could play another role, such as in CDK4/Rb/E2F transcriptional axis in the hormone-independent growth of breast cancer cells." (PMID 24564526, 2014). "However, the role of cyclin D1/CDK4/CDK6 in breast cancers is highly controversial." (PMID 23886499, 2013). "Thus, further studies are needed to establish whether inhibition of CA via the Cdk4-Nek2 pathway will improve the clinical outcome of breast cancer patients." (PMID 23776583, 2013). "BACKGROUND: Abemaciclib, a selective cyclin-dependent kinase 4 and 6 (CDK4/6) inhibitor, is standard adjuvant therapy for hormone receptor (HR)-positive, HER2-negative early breast cancer." (PMID 41535991, 2026). "Cellular experiments confirmed that DSN1 promotes breast cancer proliferation by affecting cell cycle pathways, involving key molecules such as CCNB1, CCND1, CKD1, CDK4, and CDK6." (PMID 41640445, 2026). "CDK4/6 inhibitors, used as the initial endocrine treatment for metastatic HR+/HER2− breast cancer, have demonstrated an ability to boost tumor immunogenicity and work in conjunction with PD-1 blockade to improve antitumor efficacy." (PMID 40990681, 2026). "Cyclin-dependent kinase 4/6 (CDK4/6) inhibitors are now standard therapies for hormone receptor-positive (HR+), HER2-negative advanced breast cancer." (PMID 42005211, 2026). "Preclinical studies have demonstrated synergistic antitumor activity when CDK4/6 inhibitors are combined with trastuzumab, pertuzumab, or newer HER2-targeted agents across multiple HER2+ breast cancer models." (PMID 41893011, 2026). "When combined with endocrine therapy, CDK4/6i are widely used as first‐ or second‐line treatment for patients with hormone receptor‐positive, HER2(−) advanced breast cancer." (PMID 41510186, 2026). "Combining immune checkpoint inhibitors with targeted therapies such as CDK4/6 inhibitors or PI3K inhibitors has shown potential in overcoming immune evasion and improving treatment efficacy in HR+ breast cancer." (PMID 40566067, 2025). "Cyclin-dependent kinase 4/6 (CDK4/6) inhibitors abemaciclib, palbociclib, and ribociclib, which are approved for the treatment of metastatic HR+/HER2 breast cancer, have also been examined in the adjuvant setting." (PMID 40557948, 2025). "Intriguingly, the active CDK4/Cyclin D/phospho(Tyr74)p27 complex is insensitive to palbociclib, a chemotherapeutic drug that selectively inhibits CDK4/6 and that has been recently introduced in the therapy of hormone receptor-positive (HR+)/HER- breast cancer." (PMID 39936980, 2025). "In contrast, in an HR + /HER2- breast cancer cell line, MCF7, which belongs to cluster 2, CDK4 depletion induced a more significant growth arrest." (PMID 39924553, 2025). "Further analysis shows that Simvastatin downregulates cyclin-dependent kinase 4 (CDK4), a key regulator of the G1/S cell cycle transition and a known marker of poor prognosis in breast cancer." (PMID 40864776, 2025). "Most notably, CDK4 and DNMT1 are inhibited by FDA-approved drugs for the treatment of luminal breast cancers and bone marrow diseases, respectively, despite being common essential genes." (PMID 40378956, 2025). "Abemaciclib, an oral CDK4/6 inhibitor developed by Eli Lilly, received FDA approval in September 2017 and holds distinction as the only CDK4/6 inhibitor approved for both early-stage and advanced HR+/HER2- breast cancer." (PMID 40421216, 2025). "In canonical cell cycle machinery, cyclin D1/CDK4 initiates RB phosphorylation and activates CDK2, as observed in ER+ breast cancer models." (PMID 39924553, 2025).
breast cancer (continued). "Cyclin-dependent kinase 4 and 6 inhibitors (CDK4/6i) have revolutionized the treatment landscape for breast cancer." (PMID 41247642, 2025). "A CDK4/6 inhibitor, such as palbociclib, demonstrated its efficacy in patients with treatment‐naive HR+/HER2− breast cancer experiencing visceral metastases, but those having visceral crises or aggressive visceral metastasis were excluded from the trial." (PMID 41339109, 2025). "Palbociclib is currently approved for use in breast cancer and targets CCND1 through CDK4/6 inhibition." (PMID 41326661, 2025). "Ribociclib is a selective inhibitor of CDK4 and CDK6 kinases, used in the treatment of breast cancer at both the early and advanced stages." (PMID 40422590, 2025). "To date, three distinct CDK4/CDK6 inhibitors—palbociclib, ribociclib, and abemaciclib—have been approved for use in patients with hormone receptor-positive (HR+) breast cancer." (PMID 40058234, 2025). "While CDK4/6 inhibitors (CDK4/6i) and endocrine therapy are standard-of-care for metastatic HR + /HER2- breast cancer, patient selection for durable efficacy remains undefined." (PMID 40506447, 2025). "CDK4/6i combined with endocrine therapy has demonstrated PFS and OS benefit for HR-positive and HER2-negative advanced breast cancer, as confirmed by the PALOMA, MONALEESA, and MONARCH trials." (PMID 40430137, 2025). "The confirmed efficacy of combining CDK4/6 inhibitors with endocrine therapy (ET) in HR+, HER2− early breast cancer patients in longer follow-up necessitates further investigation." (PMID 40717978, 2025). "Using drugs that inhibit enzymes called CDK4/6 and CDK2 extends the G1 phase of the cell cycle and helps to slow the growth of drug-resistant breast cancer." (PMID 41410553, 2025). "Patients presented with diverse breast cancer subtypes (luminal, HER2-positive, triple negative), and were managed with various systemic regimens, including endocrine therapy, CDK4/6 inhibitors chemotherapy, anti-HER2 agents or immune checkpoint inhibitor." (PMID 40737892, 2025). "We interrogated a large clinical cohort of patients with breast cancers which received tumor sequencing using the FDA-cleared, tumor-normal, MSK-IMPACT assay, which provides sequencing coverage spanning the CDK4 and CDK6 exonic regions." (PMID 41279360, 2025). "The optimal sequencing of CDK4/6 inhibitors combined with endocrine therapy for advanced hormone receptor-positive, HER2-negative (HR+/HER2-) breast cancer remains uncertain, particularly in resource-limited settings such as China." (PMID 41383485, 2025). "Our study further revealed that miR‐195‐5p transfection led to the downregulation of CCND3, CDK4, and PLK1 in all studied breast cancer cell lines." (PMID 40548926, 2025). "The combination of CDK4/6 inhibitors and hormone receptor antagonists has demonstrated remarkable clinical efficacy in treating ER+/HER2− breast cancer patients." (PMID 40563591, 2025). "Since 2017, cyclin-dependent kinase 4 and 6 inhibitors (CDK4/6i) have been available for patients with hormone receptor-positive advanced breast cancer." (PMID 39954390, 2025). "In estrogen receptor-positive (ER+) breast cancer, PAK1 hyperactivation mediates resistance to endocrine therapy (ET) and CDK4/6 inhibitors by driving epithelial-to-mesenchymal transition (EMT) and MAPK pathway activation." (PMID 40001545, 2025). "To evaluate the impact of continued CDK4/6i treatment in drug-resistant settings, we employed HR+/HER2− breast cancer cell lines (MCF-7, T47D, and CAMA-1) and a triple-negative breast cancer cell line (MDA-MB-231), all of which have an intact Rb/E2F pathway." (PMID 39605351, 2025). "Here, we confirmed that FGF signaling activation confers resistance to a CDK4/6 inhibitor and ET in ER+/HER2− breast cancer preclinical models, as previously reported." (PMID 40227585, 2025).
breast cancer (continued). "The Medication Assessment by Pharmacists (MAP) program at BC Cancer Surrey in Surrey, British Columbia, launched in 2019, integrates oncology pharmacists into a shared care model for patients with metastatic breast cancer receiving a CDK4/6 inhibitor." (PMID 40710212, 2025). "CDK4/6 inhibitors plus endocrine therapy is the first-line treatment for hormone receptor-positive, HER2-negative breast cancer with metastatic recurrence." (PMID 40862810, 2025). "Our meta-analysis demonstrates that the addition of CDK4/6 inhibitors to endocrine therapy can result in improved PFS and OS for HR+ breast cancer patients." (PMID 40104496, 2025). "In fact, several studies have shown that E2 controls the Cyclin D1, c-Myc, CDK2, CDK4, and CDK inhibitors in MCF-7 breast cancer cells, thus promoting the progression from the G1 to S phase of the cell cycle." (PMID 40801565, 2025). "CDK4/6 inhibitors (CDK4/6i) plus endocrine therapy (ET) have been established as a first‐line therapy for advanced hormone receptor‐positive and HER2‐negative breast cancer." (PMID 39686815, 2025). "CDK4/6 inhibitors combined with endocrine therapy continue to improve invasive disease-free survival (iDFS) in HR+, HER2-early breast cancer with longer follow-up." (PMID 40717978, 2025). "CDK4/6 inhibitors (CDK4/6i) have become the standard of care for HR+, HER2- advanced breast cancer (ABC), with efforts underway to extend their benefit through combination therapies and for use in additional populations, including those with HER2+ disease." (PMID 40144206, 2025). "In breast cancer, one study identified a subset of Cluster of Differentiation 63 (CD63+) CAFs in ER-positive breast cancer that are enriched in tumors resistant to CDK4/6 inhibitors (CDK4/6i)." (PMID 40940809, 2025). "The use of abemaciclib and ribociclib, CDK4/6 inhibitors, with letrozole in treatment of HR-positive/HER2-negative (HR+/HER2−) breast cancer was also evaluated in India taking two scenarios into consideration." (PMID 41008856, 2025). "Palbociclib was the first CDK4/6 inhibitor approved by the United States Food and Drug Administration (US FDA) in 2015; it targets HR-positive/HER2-negative breast cancer." (PMID 40861456, 2025). "This study evaluates the safety of combining CDK4/6 inhibitors with palliative radiotherapy in patients with metastatic hormone receptor-positive and HER2-negative breast cancer." (PMID 39941794, 2025). "To conclude, the introduction of CDK4/6 inhibitors, specifically Palbociclib, has transformed treatment outcomes for HR-positive and HER2-negative advanced breast cancer." (PMID 39860516, 2025). "Here, we investigated the role of FGF signaling in resistance to CDK4/6 inhibitors or ET and the effects of tasurgratinib on drug resistance in preclinical ER+/HER2− breast cancer cell lines and patient-derived xenograft (PDX) models." (PMID 40227585, 2025). "The study unveiled a critical role of NSRP1 downregulation in CDK4/6i resistance development, suggesting NSRP1 as a promising biomarker for patients with ER+ breast cancer." (PMID 39667501, 2025). "Currently, CDK4/6 inhibitors are the first-line treatment for HR+, HER2-, advanced breast cancer, with both abemaciclib and ribociclib receiving FDA approval for use in early breast cancer." (PMID 40717978, 2025). "Initially, the antitumor activities of palbociclib, a CDK4/6 inhibitor, in combination with fulvestrant, an ET, were analyzed in five established PDX models of ER+ breast cancer." (PMID 40227585, 2025). "Palbociclib, a first-in-class cyclin-dependent kinase 4/6 (CDK4/6) inhibitor developed by Pfizer, marked a paradigm shift in HR + breast cancer management." (PMID 40520159, 2025).